SMAD7 (SMAD family member 7)
Diseases named in the same sentence as SMAD7 in open-access papers (continued):
Sharing a sentence is not in itself a finding about the gene and the disease.
leiomyoma (2 papers, 2022). A well-circumscribed benign smooth muscle neoplasm characterized by the presence of spindle cells with cigar-shaped nuclei, interlacing fascicles, and a whorled pattern. "Our experiment detected a non‐significant decreased mRNA and a significantly increased protein expression of SMAD7 in response to simvastatin treatment in leiomyoma stem cells." (PMID 35118811, 2022). "We demonstrated that simvastatin reduces SMAD2 and SMAD4 expression in leiomyoma stem cells, whereas it increases the expression of the inhibitory SMAD7." (PMID 35118811, 2022). "Additionally, gonadotropin‐releasing hormone analog (GnRHa) therapy decreases TGF‐βRs, SMAD3 and SMAD4 along with an increase in SMAD7 expression in both myometrium and leiomyoma tissues compared to untreated control." (PMID 35118811, 2022). "Simvastatin significantly decreased the mRNA levels of NF‐κB by 2.00‐fold and the protein levels of phosphorylation of NF‐κBp65 by 1.54‐fold in leiomyoma stem cells compared to control, suggesting the reduction of SMAD7 activated inflammation may be via NF‐κB dependent pathway." (PMID 35118811, 2022). "Taken together, the lack of TGFβIII and the presence of SMAD7 negatively affected by the high expression of hsa-miR-595, may explain the apparent contradiction between the level of expression of the miRNAs and the upregulation of TGFβ signaling observed in leiomyoma." (PMID 35885889, 2022).
liver cirrhosis (2 papers, 2020 to 2025). "The rats with established liver cirrhosis were treated with Smad7-MSCs by direct injection of cells into the main lobes of the liver." (PMID 32928296, 2020). "The MSCs overexpressing Smad7 at passage 3 were used for in vivo cell therapy in the following liver cirrhosis model." (PMID 32928296, 2020). "Our findings provide a direct in vivo evidence that Smad7-MSC therapy is effective in the treatment of CCl4-induced liver cirrhosis." (PMID 32928296, 2020). "The expression of α-SMA was increased in the CCl4-induced liver cirrhosis group; however, the expression was significantly decreased in the group receiving Smad7-MSCs, suggesting less activity of HSCs occurred in the liver after cell therapy." (PMID 32928296, 2020). "Inhibition of TGF-β1 signalling pathway by enhancement of Smad-7 expression could be a feasible cell therapy approach to mitigate liver cirrhosis." (PMID 32928296, 2020). "As we expected, the therapeutic effect was more significant in the group treated with Smad7-MSCs comparing with the group treated with MSCs alone, suggesting that MSCs overexpressing Smad7 are more effective in the treatment of liver cirrhosis via inhibiting TGF-β1-Smad signalling pathway." (PMID 32928296, 2020). "The Smad7 mRNA was decreased in the CCl4-induced liver cirrhosis group." (PMID 32928296, 2020).
nasal polyp (2 papers, 2016 to 2023). "Parallels may be drawn between the impact of VPA and TGF-β2 on Smad6 expression and the capacity of trichostatin A, also an HDAC inhibitor, to rescue TGF-β1-suppressed Smad7 in nasal polyp-derived fibroblasts." (PMID 26507880, 2016).
oesophageal cancer (2 papers, 2020 to 2023). "The transcription factor forkhead box D3 (FOXD3) can bind directly to the promoter region of the SMAD7 gene, leading to the transcriptional promotion of SMAD7 in human oesophageal cancer cells, inhibition of the TGF-β pathway, and suppressive effects in oesophageal squamous cell carcinoma." (PMID 37685308, 2023). "A recent study has documented a Smad7 single nucleotide polymorphism (SNP) rs144204026, which leads to a transition from Glycine to Arginine in position 39 into the MH1 domain of Smad7, in a father and son with extensive hamartomatous gastrointestinal polyposis and early-onset oesophageal cancer." (PMID 32707955, 2020). "In oesophageal cancer, ATP-binding cassette, sub-family B (MDR/TAP), member 7 (ABCB7) knockdown inhibits TGF-β signalling pathway transduction by promoting SMAD7 expression and repressing SMAD3 expression, inducing apoptosis and suppressing EMT in oesophageal cancer cells." (PMID 37685308, 2023).
pancreatic ductal adenocarcinoma (2 papers, 2011 to 2022). An infiltrating adenocarcinoma that arises from the epithelial cells of the pancreas. "In the present study, we examined the differential protein expressions of Smad4, Smad6 and Smad7 in surgically resected samples of paired tumor tissue of pancreatic ductal adenocarcinoma versus adjacent normal tissue." (PMID 22195733, 2011). "Protein levels of all three Smads, Smad4, Smad6 and Smad7 were evaluated in paired normal pancreatic tissues and tumor samples of pancreatic ductal adenocarcinoma." (PMID 22195733, 2011). "This study investigates the differential protein expressions of Smad4, Smad6 and Smad7 in tumor as compared to normal tissue of pancreatic ductal adenocarcinoma (PDAC) and compares them with clinicopathological parameters and patient survival." (PMID 22195733, 2011).
Right ventricular hypertrophy (2 papers, 2021 to 2025). In this case the right ventricle is more muscular than normal, causing a characteristic boot-shaped (coeur-en-sabot) appearance as seen on anterior- posterior chest x-rays. "WT BMP9 failed to improve right ventricular systolic pressure or right ventricular hypertrophy, despite clear target engagement shown by upregulation of SMAD7." (PMID 40720495, 2025).
skin cancer (2 papers, 2016 to 2021). "The transcription of SMAD7 is upregulated in chemically induced skin tumors and TGF-β-treated normal keratinocytes." (PMID 34059951, 2021). "Perhaps the Smad7Δ upregulation in skin tumors observed in our study is a mechanism to antagonize the impact of Smad7 increase and restore selective responses to TGF-β." (PMID 27536941, 2016). "Smad7 acts as a promoter of chemically induced skin cancers." (PMID 34059951, 2021). "JARID1B and TIEG1 inhibit SMAD7 transcriptional activity and antagonize skin cancer development." (PMID 34059951, 2021).
steatosis (2 papers, 2011 to 2022). Increased lipid within the cytoplasm of cells. "In addition, alcohol-induced liver injury and steatosis were profoundly aggravated in Smad7 deficient mice, associated with upregulation of critical genes involved in lipogenesis and inflammation." (PMID 21386907, 2011). "Together, these data suggest that the liver injury and steatosis induced by chronic alcohol administration were enhanced by Smad7 deletion, further indicating that Smad7 deletion has a deteriorating effect on liver functions." (PMID 21386907, 2011). "Furthermore, hepatic injury and steatosis induced by chronic alcohol exposure were accelerated by Smad7 deletion." (PMID 21386907, 2011). "Combining these results, we propose that the alteration of ethanol metabolism, lipogenesis and inflammatory response caused by Smad7 deletion may act together to contribute to severe alcoholic liver injury and steatosis in Smad7-deleted mice." (PMID 21386907, 2011).
thyroid cancer (2 papers, 2023). "For example, studies have shown that in thyroid cancer reg γ binds directly to the TGF-β signaling antagonist SMAD7 and promotes its degradation, leading to the activation of the TGF-β signaling pathway." (PMID 37848968, 2023). "Some studies have reported a frequent overexpression of Smad-4 and Smad-7 in thyroid cancer." (PMID 37905271, 2023).
type 2 diabetes (2 papers, 2013 to 2016). "In addition, the SMAD7 SNP rs3764482 (IVS2 –21C>T) has been associated with a reduced risk of type 2 diabetes in mice." (PMID 23560096, 2013).
virus infection (2 papers, 2019 to 2022). "Some anti-fibrotic factors, namely SMAD6, SMAD7, STAT1, and HGF, were also induced by the virus infection, although to a lesser extent compared to pro-fibrotic upregulation, perhaps as a counterbalance of the potent pro-fibrotic expression induced in vitro by virus infection." (PMID 31878218, 2019).
acute pancreatitis (1 paper, 2014). An acute inflammatory process that leads to necrosis of the pancreatic parenchyma. "Bronchial epithelial cells as well as vascular endothelial, smooth muscle, and inflammatory cells showed considerably higher levels of Smad7 9 h after acute pancreatitis induction compared to sham controls." (PMID 24688224, 2014). "The anti-inflammatory activities of increased Smad7 at early phase in our model can be interpreted as a protective mechanism in the lungs of the animals with acute pancreatitis." (PMID 24688224, 2014). "Inhibitory Smad7 expression was transiently increased at 9 h in acute pancreatitis, but reduced later at 24 h, with a concomitant increased nuclear translocation of phosphorylated Smad2." (PMID 24688224, 2014).
age-related macular degeneration (1 paper, 2022). Age-related loss of vision in the central portion of the retina (macula), secondary to retinal degeneration. "H2O2 increased iron concentration in retinal pigment epithelial cells via the BMP6/SMAD/hepcidin axis, resulting in age-related macular degeneration.Inhibitory SMAD7 is a key repressor of hepcidin, the master regulator of systemic iron homeostasis." (PMID 36398315, 2022).
alcoholic fatty liver disease (1 paper, 2021). Lipid infiltration of the hepatic parenchymal cells that is due to alcohol abuse. "Smad7 deficiency contributes to the development of alcoholic fatty liver disease." (PMID 34568346, 2021).
allergic asthma (1 paper, 2010). A asthma with a basis in a pathological type I hypersensitivity reaction. "Collectively, these data indicate that Smad7 expression in airway epithelial cells was able to alleviate local inflammation, matrix deposition and mucus secretion in OVA-induced allergic asthma." (PMID 20405019, 2010). "Our data uncover for the first time that specifically blocking the TGF-β signaling by overexpression Smad7 in lung epithelium, but not in immune cells, is sufficient to relieve the development of allergic asthma." (PMID 20405019, 2010).
anhidrosis (1 paper, 2021). Lack of sweating or the ability to sweat when provoked by the appropriate stimulus. "Specifically, SMAD Family Member 7 (SMAD7) was upregulated 5.71-fold during erythromycin-induced anhidrosis." (PMID 34944156, 2021).
astrocytoma (1 paper, 2017). "Moreover, high expression of 7 of the high-malignant genes (C7ORF46, DUSP4, HS3ST3B1, ODZ1, TTL, VAV3, ZDHHC23) or low expression of 4 of the low-malignant genes (AKR1C3, ARHGEF10L, SMAD7, ST3GAL6) was associated with a lower progression free survival probability of grade III astrocytoma patients." (PMID 29152145, 2017).
carotid atherosclerosis (1 paper, 2020). A thickening and loss of elasticity of the walls of carotid arteries that occur with formation of atherosclerotic plaques. "Moreover, in human carotid atherosclerosis plaque tissues, Smad7 mRNA expression level markedly decreased in the high miR-216a group in comparison with the low miR-216a group, suggesting a negative regulation of miR-216a on the Smad7 expression within human atherosclerotic lesions." (PMID 33282009, 2020).
chronic asthma (1 paper, 2024). An asthma that is characterized by the development of persistent airway inflammation and recurrent attacks of breathlessness and wheezing, which vary in severity and frequency. "In another study of a chronic asthma rat model treated with resveratrol, the phosphorylated SMAD2 and SMAD4 levels were reported to be decreased, but no change was observed in SMAD7 protein expression." (PMID 39055873, 2024).
Chronic colitis (1 paper, 2010). A chronic inflammatory disease of the large intestine (colon, cecum and rectum). "In wt mice with chronic colitis, IL-23a, IL-13, NF-kB2, PTGS1, SMAD3 and SMAD7 (P≤0.05) were significantly down-regulated, with the largest variations affecting the expression of IL-23a and IL-13 (100- and 10-fold)." (PMID 20706593, 2010).
cognitive decline (1 paper, 2023). "However, the underlying mechanism of TGF-β- and Smad7-induced apoptosis in postoperation cognitive decline is unclear." (PMID 37507781, 2023). "When the expression of Smad7 was knocked down by shRNA, neuroinflammation and apoptosis were significantly reduced and further attenuated cognitive decline postsurgery." (PMID 37507781, 2023). "Taken together, these results suggested that the increased expression of Smad7 in hippocampal neurons might play a vital role in the development of cognitive decline induced by anesthesia surgery." (PMID 37507781, 2023). "Meanwhile, the increased expression of Smad7 and TGF-β simultaneously induced apoptosis in the hippocampus, which also had an adverse function in the development of cognitive decline after unilateral nephrectomy." (PMID 37507781, 2023). "In the present work, the results demonstrated that the specific downregulation of Smad7 in the hippocampal CA1 region indeed protected mice from neuroinflammation after unilateral nephrectomy, which further improved the cognitive decline induced by anesthesia surgery." (PMID 37507781, 2023).
coloboma (1 paper, 2018). An abnormality in which a part of a structure in one or both eyes is missing. "In mouse, knockout of the Smad7 gene led to various eye defects including coloboma." (PMID 29593116, 2018).
colorectal tumors (1 paper, 2013). "Both deletions and amplifications of the Smad7 gene have been reported in colorectal tumors." (PMID 24047375, 2013).
congenital heart disease (1 paper, 2013). "Therefore, it was hypothesized that SMAD7 might be associated with the risk of congenital heart defects in humans." (PMID 24039762, 2013). "SMAD7 is a general antagonist of TGF-β signaling and has been found to be involved in cardiogenesis in mouse models, but its role in human congenital heart disease (CHD) has yet to be investigated." (PMID 24039762, 2013).
disc degeneration (1 paper, 2022). "Our previous study also has demonstrated that Smad7 plays key roles in disc degeneration." (PMID 35795857, 2022). "Smad7 may be a potential target for the prevention and treatment of degenerative disc disease." (PMID 35795857, 2022). "Although IL-1β is proved to be able to induce disc cell apoptosis and disc degeneration, the expression of Smad7 in the AF cells under IL-1β stimulation has never been described." (PMID 35795857, 2022).
esophageal squamous cell carcinoma (1 paper, 2016). Esophageal squamous cell carcinoma (ESCC) is a type of esophageal carcinoma (EC) that can affect any part of the esophagus, but is usually located in the upper or middle third. "Thus, our results further proved that SMAD7 signaling pathway participated in the miR-424-5p regulated EMT in esophageal squamous cell carcinoma." (PMID 27628042, 2016).
esophageal tumour (1 paper, 2020). "Previous immunohistochemical evaluation of esophageal tumour specimens demonstrated intact levels of Smad7 protein expression in the patients carrying on such a variant." (PMID 32707955, 2020).
fasciolosis (1 paper, 2016). "Considering that fibrosis is often limited in ovine as compared with bovine fasciolosis, it would be interesting to investigate the transcription of SMAD7 during F. hepatica infection in cattle." (PMID 27661612, 2016). "This indicates that SMAD7 may play a negative regulatory role in fibrosis formation during the chronic stage of ovine fasciolosis." (PMID 27661612, 2016). "The inhibitory-Smad protein (SMAD7) may play a key role in limitation of fibrosis formation in ovine fasciolosis." (PMID 27661612, 2016). "SMAD7 is involved in a negative feedback loop which can suppress the fibrogenic progress mediated by SMAD2/3/4 signaling, indicating that SMAD7 may play a role in controlling fibrosis during the early stage of ovine fasciolosis." (PMID 27661612, 2016).
fatty liver (1 paper, 2011). "In our study, we also found that loss of Smad7 function is accompanied by enhancement of alcoholic hepatic steatosis, further indicating the importance of TGF-β signaling in the development of alcohol-induced liver damage." (PMID 21386907, 2011). "We also found that Smad7 deficiency is able to enhance formation of alcohol-induced fatty liver." (PMID 21386907, 2011). "Furthermore, the alcohol-induced liver steatosis was profoundly enhanced by Smad7 deletion." (PMID 21386907, 2011).
gastric adenocarcinoma (1 paper, 2015). "In one study, the expression of the common SMAD mediator Smad4 and the inhibitory SMAD protein Smad7 was examined in gastric adenocarcinomas." (PMID 26583078, 2015). "However, Smad7 expression in well-differentiated gastric adenocarcinomas was significantly higher than that in the normal gastric mucosa and associated with the duration of disease-free survival." (PMID 26583078, 2015). "In human gastric adenocarcinoma AGS cells, H. pylori-stimulated mononuclear cells (MNCs) in the lamina propria express the TGF-β pathway inhibitory factor Smad7." (PMID 26583078, 2015).
gastritis (1 paper, 2023). Inflammation of the stomach. "The feedback loop, including TGF-b1, Smad-7, and CTGF, could be involved in the pathogenesis of H. pylori–associated gastritis." (PMID 37037466, 2023).
Hyperammonemia (1 paper, 2023). An increased concentration of ammonia in the blood. "We show that hyperammonemia reduces the content of Smad7 and IkB in hippocampus, which are restored by treatment with EVs from MSCs and also by treatment with recombinant TGFβ." (PMID 36593485, 2023). "We found that hyperammonemia reduced Smad7 content in hippocampus (79 ± 5% of control, p < 0.05) and this is associated with a parallel reduction of the IkB content (81 ± 2% of control, p < 0.001)." (PMID 36593485, 2023).
Hypoinsulinemia (1 paper, 2012). A decreased concentration of insulin in the blood. "In addition, conditional expression of the inhibitory Smad7 in β-cells resulted in reduced pancreatic insulin levels and in hypoinsulinemia." (PMID 22359515, 2012).
infertile (1 paper, 2022). "Our study suggested that weight loss over 10kg in PCOS infertile patients can significantly reduce the expression of Smad7, thus improving the regulation of TGF-β signaling pathway, which in turn increases follicle quality and improves pregnancy outcome." (PMID 36246893, 2022).
intervertebral disc degeneration (1 paper, 2022). "As a downstream molecule of TGF-β1, exploring the role and mechanism of Smad7 in intervertebral disc degeneration has grabbed our interest." (PMID 35795857, 2022). "Combined with the finding in our previous animal study that the expression of Smad7 significantly increased in the degenerative discs of rats, we verified that Smad7 should be involved in the pathophysiological process of intervertebral disc degeneration." (PMID 35795857, 2022).
invasive breast carcinoma (1 paper, 2013). A carcinoma that infiltrates the breast parenchyma. "Theohari and colleagues investigated the expression of Smad7 in 150 invasive breast carcinoma specimens and showed that Smad7 levels positively correlate with tumor size, stage, matrix metalloproteinase (MMP)-9 and MMP-14 expression thus resulting in an aggressive phenotype." (PMID 24317436, 2013).
Kawasaki disease (1 paper, 2019). A rare inflammatory disease characterized by an acute febrile, systemic, self-limiting, medium-vessel vasculitis primarily affecting children. "For example, up-regulated miR-27b in the serum of Kawasaki disease patients enhanced endothelial cell proliferation and migration by targeting Smad7." (PMID 31930115, 2019).
kidney stone (1 paper, 2019). "PPAR-γ is upstream of the HGF/c-Met signaling pathway and can regulate the activation of Smad7; therefore, we determined whether PPAR-γ regulates the expression of HGF, c-Met, and Smad7 in renal tubular epithelial cells during kidney stone formation." (PMID 31781338, 2019).
larynx (1 paper, 2010). "However, data concerning Smad7 seems to be more controversial since our own present data indicates that Smad7 mRNA low expression correlates with shorter survival in larynx SCC." (PMID 20462450, 2010). "In addition, Smad7 high mRNA expression correlated with shorter survival in patients with larynx SCC submitted to curative surgery." (PMID 20462450, 2010).